SMAD2 (SMAD family member 2)
Diseases named in the same sentence as SMAD2 in open-access papers (continued):
Sharing a sentence is not in itself a finding about the gene and the disease.
pancreatic cancer (continued). "Disruption of cholesterol biosynthesis by Nsdhl knockout or statins treatment also induced SREBP1-dependent Tgfb1 expression and autocrine TGF-β-SMAD2/3 signaling in pancreatic cancer cells." (PMID 34621019, 2021). "In our study, we found that HNK can inhibit the PNI of pancreatic cancer in several aspects via regulating SMAD2/3 signaling." (PMID 34671554, 2021). "In the cancer cell-DRG coculture system, we found that activating SMAD2/3 of pancreatic cancer cells can promote the crosstalk between cancer cells and nerves by increasing the cancer cell invasion index and the DRG axon growth index." (PMID 34671554, 2021). "Further investigation of the effect of SMAD2/3 activation on PNI in pancreatic cancer revealed that activating SMAD2/3 signaling increased the cancer cell invasion index and the DRG axon growth index." (PMID 34671554, 2021). "In conclusion, our data provide strong evidence for H19-mediated APOBEC3G expression, which in turn activates TGF-β/Smad2 signaling and thereby contributes to the progression of pancreatic cancer, and this process is inhibited by sulforaphane." (PMID 33669381, 2021). "Our studies show that integrin β1 regulates TGF-β receptor-2 expression levels and Smad2/3 dependent intracellular cell signaling in pancreatic cancer." (PMID 34638957, 2021). "In the present work, we demonstrated that CAFs secrete TGF-β1 to upregulate the expression of ATF4 in pancreatic cancer cells via the SMAD2/3 pathway." (PMID 33782384, 2021). "The HNK-mediated suppression of pancreatic cancer PNI was partially mediated by inhibition of SMAD2/3 phosphorylation." (PMID 34671554, 2021). "We demonstrated that TGF-β1 derived from CAFs upregulates the expression level of ATF4 in pancreatic cancer cells via the SMAD2/3 pathway." (PMID 33782384, 2021). "Previous data with pancreatic cancer cells have shown that Rac1b acts as an endogenous inhibitor of TGF-β signaling by interfering with Smad2/3 activation." (PMID 28726720, 2017). "In human pancreatic cancer Panc-1 cells, results from knockdown of TGFβ signaling mediators Smad2 and Smad3 demonstrated an opposite function of Smad2 versus Smad3 on TGFβ-induced cell migration." (PMID 29379802, 2017). "Taken together, our findings demonstrate that HS-173 can efficiently suppress EMT and metastasis by inhibiting PI3K/AKT/mTOR and Smad2/3 signaling pathways, suggesting it can be a potential candidate for the treatment of advanced stage pancreatic cancer." (PMID 27793006, 2016). "Of note, a recent study shows that the overexpression of Nodal induces a metastatic phenotype in pancreatic cancer cells via the Smad2/3 pathway." (PMID 26220524, 2015). "Here, we expanded this preliminary finding and verified that Nodal enhances CXCR4 expression in pancreatic cancer cells via the Smad2/3 pathway in vitro." (PMID 25557170, 2015). "Recently, we found that CAFs promote gemcitabine resistance in pancreatic cancer via the TGF-β1/SMAD2/3 pathway and ABCC1 transactivation and revealed that epigenetic modification mechanisms drive gemcitabine resistance in PDAC via LLGL1-associated phosphorylation of ER signaling pathway components." (PMID 35264742, 2022). "In addition, downregulation of GPC-1 attenuated TGF-β1 signaling and Smad2 phosphorylation to suppress pancreatic cancer cell growth." (PMID 36313694, 2022). "In conclusion, rhoifolin regulates the AKT/JNK/caspase-3 and TGF-β2/SMAD2 signaling pathways, which may contribute to its anti-pancreatic cancer effects." (PMID 35383226, 2022). "Lnc00462 promotes the progression of pancreatic cancer through the molecular mechanism of ceRNA and serves as a molecular sponge for miR-665 to upregulate TGF-βRI and TGF-βRII and activate the Smad2/3 signaling pathway to enhance the invasive ability of pancreatic cancer." (PMID 35819532, 2022).
pancreatic cancer (continued). "In addition, the RT-PCR and Western blot analyses also revealed that the TFCP2 overexpression significantly promoted the transcription of the SMAD2 gene in pancreatic cancer cells." (PMID 35193647, 2022). "The RT-PCR and Western blot analyses showed that the TFCP2 silencing could significantly inhibit the transcription of the SMAD2 gene in the pancreatic cancer cells." (PMID 35193647, 2022). "The present study previously found that the ITGA2 could inhibit the SMAD2 expression by interacting with TFCP2 in the pancreatic cancer cells." (PMID 35193647, 2022). "Therefore, SMAD2 upregulation mediated the anti-tumor effect of ITGA2 silencing in pancreatic cancer, which represents treatment by inducing the SMAD2 expression as a novel therapeutic strategy for pancreatic cancer." (PMID 35193647, 2022). "Taken together, these results indicated that the ITGA2 could inhibit the SMAD2 expression by interacting with TFCP2 in the pancreatic cancer cells." (PMID 35193647, 2022). "MiR-455 suppressed cell growth and invasion through targeting SMAD2 in pancreatic cancer cells." (PMID 34539879, 2021). "To explore whether SMAD2 or SMAD3 is responsible for the PNI of pancreatic cancer, we designed siRNA to knockdown SMAD2 and SAMD3 in PANC-1 cell line respectively." (PMID 34671554, 2021). "DLEU2 blocked miR-455-mediated targeting of SMAD2 in pancreatic cancer cells." (PMID 34178644, 2021). "SMAD2 promoted invasive potential of pancreatic cancer cells." (PMID 34178644, 2021). "In addition, our results show that HNK suppresses perineural invasion of pancreatic cancer by inhibiting SMAD2/3 signaling." (PMID 34671554, 2021). "Therefore, we revealed that HNK suppresses perineural invasion by inhibiting SMAD2/3 signaling in pancreatic cancer." (PMID 34671554, 2021). "TGF-β1/SMAD2/3 signaling contributes to PNI in pancreatic cancer." (PMID 34671554, 2021). "To confirm whether pancreatic cancer cells are TGF-β1 responsive, we determined the effects of exogenous TGF-β1 on migration, invasion, and Smad2/3 phosphorylation in pancreatic cancer cells." (PMID 32848128, 2020). "We found that either pancreatic cancer-derived EVs or TGF-β1 could induce the phosphorylation of Smad2/3 in NK cells." (PMID 31234517, 2019). "The signalling cascade through the complex Smad2/3/4 may be very important in some type of pancreatic cancer cells as Smad4 is a critical mediator of TGFβ signalling." (PMID 29064388, 2017). "Also, HS-173 reduced EMT by increasing epithelial markers and decreasing the mesenchymal markers by blocking the PI3K/AKT/mTOR and Smad2/3 signaling pathways in pancreatic cancer cells." (PMID 27793006, 2016). "Further studies should focus on whether Nodal elevation in pancreatic cancer induces a Smad2/3-independent pathway." (PMID 25557170, 2015). "Similarly, the overexpression of ITGA2 could inhibit the expression of SMAD2 and phosphorylation of SMAD2/3 in the pancreatic cancer cell." (PMID 35193647, 2022). "In addition, linc00462 promotes the invasiveness of pancreatic cancer cells via regulating the miR-665/TGFBR1-TGFBR2/SMAD2/3 pathway, hence it could promote cell progression." (PMID 35310430, 2022). "However, it is not completely clear whether rhoifolin blocks tumor angiogenesis and metastasis in pancreatic cancer through the TGF-β2/SMAD2 pathway." (PMID 35383226, 2022). "Therefore, it was supposed that the ITGA2 could inhibit the SMAD2 expression via TFCP2 in the pancreatic cancer cells." (PMID 35193647, 2022). "We hypothesize that activating SMAD2/3 can promote PNI in pancreatic cancer." (PMID 34671554, 2021). "Therefore, we investigated whether pancreatic cancer-derived EVs could activate the TGFβ-Smad2/3 signaling pathway in NK cells." (PMID 31234517, 2019). "Continuously activated KRAS signaling in pancreatic cancer cells activates RREB1, which promote the binding of SMAD2/3 to the cis-regulatory regions of target genes." (PMID 39913299, 2025).
pancreatic cancer (continued). "For example, pancreatic cancer-derived EVs inhibit NK cell function by delivering TGF-β1 to NK cells and inducing Smad2/3 phosphorylation." (PMID 37834100, 2023). "For example, lnc00462 promotes pancreatic cancer invasiveness and metastasis through the miR-665/TGF-βRI-TGF-βRII/SMAD2/3 pathway." (PMID 35819532, 2022). "The ITGA2 inhibited the SMAD2 expression by interacting with TFCP2 and inhibiting its nuclear translocation in the pancreatic cancer cells." (PMID 35193647, 2022). "Functional activation and overexpression of the components of the activin/nodal signaling pathway including Nodal, Cripto-1, FoxH1, Smad2, Smad4, Gdf1, activin, and ACVR1B were detected in primary pancreatic cancer stem cells (CSC)." (PMID 34356885, 2021). "LINC00462 participates in the miR-666/TGFBR1-TGFBR2/SMAD2/3 or AKT signaling pathways to promote tumor invasion and progression in pancreatic cancer and hepatic cancer." (PMID 34238114, 2021). "Here, we report that activating SMAD2/3 by TGF-β1 can also induce EMT and the invasion and migration of pancreatic cancer cells." (PMID 34671554, 2021). "More importantly, activating SMAD2/3 can upregulate the expression of NGF and BDNF in pancreatic cancer cells and promote the PNI of pancreatic cancer in vitro." (PMID 34671554, 2021). "Reduced GPC-1 expression attenuated the TGF-β1 induced inhibition of cell growth, with suppressed Smad2 phosphorylation, and plasminogen activator inhibitor-1(PAI-1) promoter activity in pancreatic cancer cells." (PMID 31355137, 2019). "Unexpectedly, the report disclosed an increase in phospho-Smad2-Ser465/467 and phospho-VEGFR2-Tyr1175 in the pancreatic tumor lysates from the OP treated cohort compared to the untreated cohort." (PMID 26932374, 2014). "To date, there are many reports regarding the TGF-β signalling pathway in pancreatic cancer (e.g. TGF-β receptor II, Smad2 and Smad4), but only a few deal with this gene’s alterations in pancreatic cancer." (PMID 18475302, 2008). "Besides, the biological functions of these proteins were detected using the colony formation assay and CCK8 cell proliferation assay in pancreatic cancer cells with ITGA2 and/or SMAD2 genes silenced." (PMID 35193647, 2022). "In pancreatic cancer, upregulation of Mena activates EMT induced by TGF-β1/Smad2 pathway." (PMID 36620546, 2022). "Here, our findings support that SMAD2/3 mediate oncogenic properties of TGFβ in the absence of SMAD4 in pancreatic tumor cells, by conferring them a collective migratory ability through modulation of Rho/Rac and FAK activities to form FA." (PMID 36207615, 2022). "ITGA2 inhibited the SMAD2 expression by interacting with TFCP2 but did not change the TFCP2 expression in the pancreatic cancer cells." (PMID 35193647, 2022). "Our results demonstrate that HNK can inhibit the invasion, migration, and PNI of pancreatic cancer by blocking SMAD2/3 phosphorylation, and we conclude that HNK may be a new strategy for suppressing PNI in pancreatic cancer." (PMID 34671554, 2021). "Besides, studies have shown that TRIM33 can participate in the TGF-β signaling pathway by binding to phosphorylated SMAD2/3 or monoubiquitinated SMAD4 in hepatocellular carcinoma, human chronic myelomonocytic leukemia, and pancreatic cancer." (PMID 32908919, 2020). "Another in vitro study in pancreatic cancer demonstrated that itraconazole inhibit viability, induce apoptosis and suppress invasion and migration by impaired transforming growth factor beta (TGF-β)/mothers against decapentaplegic homolog 2/3 (SMAD2/3) signalling." (PMID 33092251, 2020).
pancreatic cancer (continued). "In addition, preliminary experiments in pancreatic cancer tissue culture cell lines demonstrate that the activin neutralizing antibody blocks activin functions as measured by a decrease in SMAD2 phosphorylation (data not shown)." (PMID 28986573, 2017). "Furthermore, the overexpression of ITGA2 could significantly inhibit the mRNA level of SMAD2 in pancreatic cancer cells, but not those of the SMAD3 or SMAD4." (PMID 35193647, 2022). "CPAE emerges as a promising herbal medicine for pancreatic cancer treatment, with its potential mediated through apoptosis induction via the caspase-dependent PARP pathway and MET suppression via the TGF-β1/Smad2/3 signaling pathway at non-cytotoxic doses." (PMID 38881872, 2024). "Pancreatic cancer cells incubated with IORT-treated PF for 4 h displayed activated cytokine-related signalling pathways (PI3K-Akt, Smad2/3) compared with cells incubated with no IORT-treated PF." (PMID 34641806, 2021).
hepatocellular carcinoma (71 papers, 2012 to 2025). A malignant tumor that arises from hepatocytes. "For example, mutations of Smad2 were found in cervical cancer, colorectal cancer and hepatocellular carcinoma." (PMID 31632911, 2019). "TOP2A may promote hepatocellular carcinoma progression by facilitating epithelial‐mesenchymal transition mediated by the p‐ERK1/2/p‐SMAD2/Snail pathway, which has been associated with a poor prognosis in hepatocellular carcinoma." (PMID 38661103, 2024). "By contrast, SMAD2 mutations have been reported in hepatocellular carcinoma (HCC)." (PMID 37892233, 2023). "Glabridin suppressed cancer stem-cell-like features in hepatocellular carcinoma cells by the upregulation of miR-148a that targets SMAD2 (mothers against decapentaplegic homolog 2) associated with the inhibition of TGF (transforming growth factor)-β/SMAD2 signaling." (PMID 38004113, 2023). "Notably, mutations in the SMAD2/4-binding sites abrogated the role of lnc-UTGF in promoting migration of hepatoma cells, suggesting that lnc-UTGF may promote migration/invasion via SMAD2/4." (PMID 34785655, 2021). "Collectively, these findings indicate that the Smad2/3/4 complex undergoes liquid–liquid phase separation in Hepatoma cells." (PMID 38769521, 2024). "Western blot results showed that Smad2/3/4 complex would active caspase-9 through TAT, which uncovered the mechanism of Smad2/3/4 complex inducing hepatoma cell apoptosis." (PMID 38769521, 2024). "Interference with circ-DOCK1 (circ_0020397) inhibits hepatocellular carcinoma cell proliferation, invasion and migration via the miR‐654‐5p/SMAD2 axis." (PMID 38570856, 2024). "Reduced TIF1-γ also promotes the metastatic capacity of hepatocellular cancer by facilitating Smad2/3/4 complex formation, resulting in poor prognosis." (PMID 37573347, 2023). "FXR1 can promote the proliferation, invasion, and migration of hepatocellular carcinoma, and its action is mediated by Smad2/3." (PMID 37517087, 2023). "Our data indicated that miR-582-3p is closely related to the overall survival rate of hepatocellular carcinoma patients and directly combines with SMAD2 to regulate its expression." (PMID 35386287, 2022). "In conclusion, our findings confirm that miR-582-3p is an independent factor for the prognosis of hepatocellular carcinoma patients, and can regulate the progression of hepatocellular carcinoma cells by targeting SMAD2." (PMID 35386287, 2022). "For example, BUB1 can enhance the proliferation of hepatocellular carcinoma cells by activating the phosphorylation of SMAD2, and BUB1B promotes liver cancer progression by activating the mechanistic target of rapamycin complex 1 (mTORC1) signaling pathway." (PMID 35493295, 2022). "Various malignancies where the mutation rate of Smad2 occurs at a low frequency are non small cell lung carcinoma (NSCLC) 2%, hepatocellular carcinoma (HCC) 3%, colorectal cancer 8% and cervical cancers 8%." (PMID 35295334, 2022). "Interfering with the expression of SMAD2 can regulate the expression of miR-582-3p and its proliferative activity on hepatocellular carcinoma cells." (PMID 35386287, 2022). "The levels of TGF-βR2, phosphorylated Smad2/3, and the genes associated with the TGF-β signaling pathway were significantly increased in hepatocellular carcinoma (HCC) lesions of TAK1ΔHEP mice compared with wild-type normal livers." (PMID 34722513, 2021). "Subsequent gain- and loss-of-function analyses disclosed that lnc-UTGF promoted the migration and invasion of hepatoma cells, and this effect of lnc-UTGF was attenuated by repressing SMAD2/4 expression or by mutating the SMAD2/4-binding sites in lnc-UTGF." (PMID 34785655, 2021). "Activin A increases VEGF expression via the physical interaction of SMAD2 with the MAPK-regulated transcription factor SP1 in hepatocellular carcinoma." (PMID 32970737, 2020).